URM1 (ubiquitin related modifier 1)
Description:
Acts as a sulfur carrier required for 2-thiolation of mcm(5)S(2)U at tRNA wobble positions of cytosolic tRNA(Lys), tRNA(Glu) and tRNA(Gln). Serves as sulfur donor in tRNA 2-thiolation reaction by being thiocarboxylated (-COSH) at its C-terminus by MOCS3. The sulfur is then transferred to tRNA to form 2-thiolation of mcm(5)S(2)U. Also acts as a ubiquitin-like protein (UBL) that is covalently conjugated via an isopeptide bond to lysine residues of target proteins such as MOCS3, ATPBD3, CTU2, USP15 and CAS. The thiocarboxylated form serves as substrate for conjugation and oxidative stress specifically induces the formation of UBL-protein conjugates.
Synonyms: C9orf74; MGC2668
Tractability: PROTAC: its protein half-life has been measured.
Gene: Protein-coding gene on chromosome 9 (128,371,349 to 128,392,016, forward strand). Ensembl gene ENSG00000167118.
Subcellular location: Cytoplasm, cytosol; Nucleus
Subcellular location (Human Protein Atlas): Vesicles; Nucleoplasm
Pathways (Reactome):
Metabolism of RNA: tRNA modification in the nucleus and cytosol
Gene Ontology:
Molecular function: protein binding; sulfur carrier activity; protein tag activity
Biological process: tRNA thio-modification; tRNA wobble uridine modification; protein urmylation
Cellular component: cytosol; nucleus; cytoplasm
Genetic constraint (gnomAD): Loss-of-function variants: 10 observed, 17.2 expected, observed/expected ratio (o/e) 0.58, 90% interval 0.36 to 0.99. The upper end of that interval is the gene's LOEUF score, 0.99, which puts it in group 4 of 6, group 1 being the genes least tolerant of losing a copy. Missense variants: 125 observed, 130.12 expected, observed/expected ratio (o/e) 0.96, 90% interval 0.83 to 1.11. Synonymous variants: 46 observed, 52.61 expected, observed/expected ratio (o/e) 0.87, 90% interval 0.69 to 1.12.
Homologues: Orthologues: rabbit URM1 (93% identical), guinea pig URM1 (90% identical), mouse Urm1 (89% identical), pig URM1 (89% identical), chimpanzee URM1 (80% identical), dog URM1 (77% identical), macaque URM1 (77% identical), rat Urm1 (75% identical), zebrafish urm1 (72% identical), tropical clawed frog urm1 (71% identical), Drosophila melanogaster Urm1 (59% identical), Caenorhabditis elegans urm-1 (30% identical).
Diseases named in the same sentence as URM1 in open-access papers:
URM1 is named in the same sentence as 6 diseases in open-access papers, as found by Europe PMC text mining. Sharing a sentence is not in itself a finding about the gene and the disease. The quoted sentences say what the papers report.
breast carcinoma (1 paper, 2023). "Collectively, these data implicate URM-1 in the breast cancer cell malignant phenotype, presumably due to the loss of Cx43 in cells downregulating URM-1." (PMID 36769280, 2023). "Given the tumor suppressor role of Cx43 in breast cancer and the apparent modulation of Cx43 by URM-1 levels in breast cancer cell lines, cells were evaluated for changes in the levels of EMT markers upon URM-1 downregulation." (PMID 36769280, 2023). "Here, we investigated the interaction of Cx43 with the ubiquitin-related modifier 1 (URM-1) protein and its impact on tumor progression in two breast cancer cell lines, highly metastatic triple-negative MDA-MB-231 and luminal breast cancer MCF-7 cell lines." (PMID 36769280, 2023). "The upregulation of URM-1 seems to, at least partially, reverse EMT in breast cancer cells." (PMID 36769280, 2023).
liver diseases (1 paper, 2026). "Bioinformatic analysis further reveals that genetic knockdown of NAE1, UBE2M, and URM1 affects overlapping genes associated with pathways controlling cellular response to stress conditions or with implications in liver diseases." (PMID 42056084, 2026).
thyroid cancer (1 paper, 2023). "To explore the role of ubiquitin-like proteins (ISG15, ATG8, FAT10, NEDD8, SUMO1, UFM1, URM1 and ATG12) in thyroid cancer, we integrated the datasets (GSE33630, GSE29265 and GSE76039) and analyzed 65 NT, 69 PTC and 40 ATC samples." (PMID 37501099, 2023).
infection (3 papers, 2019 to 2022). The state of being infected such as from the introduction of a foreign agent such as serum, vaccine, antigenic substance or organism. "Variance analysis showed that knockout of Urm1 significantly reduced the pathogenicity of T. gondii in the two infection dose groups." (PMID 35323018, 2022). "In this study, we identified URM1 as another component of the detoxification systems, which is used to counteract host oxidative stress for infection of M. oryzae." (PMID 31551975, 2019). "Here, we describe a ubiquitin-like protein URM1, and found it plays important roles in the development and infection process of the rice blast fungus, Magnaporthe oryzae." (PMID 31551975, 2019). "Taken together, URM1 is required for invasive growth in the barley host cells during infection." (PMID 31551975, 2019). "Some of the mutants had earlier decay of the primary roots after the onset of infection and could not develop to a later stage, such as atg8e, urm1." (PMID 36247580, 2022).
cancer (2 papers, 2018 to 2021). A tumor composed of atypical neoplastic, often pleomorphic cells that invade other tissues. "In summary, the evidence that implicates the Urm1 pathway in disease, renders it very promising to establish the Urm1-Uba4-system as a novel drug target to inhibit translational processes in cancer." (PMID 33499055, 2021). "Only three genes including Dolichol Kinase (DOLK), TruB Pseudouridine Synthase Family Member 2 (TRUB2), and Ubiquitin Related Modifier 1 (URM1) were identical between normal and cancer tissues." (PMID 30388870, 2018).
tumor (1 paper, 2023). "Conversely, the upregulation of URM-1 upregulated Cx43 expression and reversed EMT-induced processes, highlighting the implication of this PTM in Cx43 tumor suppression properties." (PMID 36769280, 2023).